WNT4 (Wnt family member 4)
Diseases named in the same sentence as WNT4 in open-access papers (continued):
Sharing a sentence is not in itself a finding about the gene and the disease.
vitamin D deficiency (1 paper, 2025). A nutritional condition produced by a deficiency of VITAMIN D in the diet, insufficient production of vitamin D in the skin, inadequate absorption of vitamin D from the diet, or abnormal conversion of vitamin D to its bioactive metabolites. "To further explore the molecular impact of vitamin D deficiency on uterine function, we examined the expression of decidual marker genes, including Bmp2, Wnt4, Prl8a2, and Pgr, using qRT-PCR." (PMID 41292920, 2025).
tumor (58 papers, 2010 to 2026). "Our data support that the SNP has implications beyond risk, in tumor biology including WNT4 signaling and metabolic remodeling." (PMID 38112643, 2024). "Understanding WNT4 dysregulation by estrogen and genetic polymorphism offers new opportunities for defining tumor biology, precision therapeutics, and personalized cancer risk assessment." (PMID 38112643, 2024). "We performed reverse phase protein array (RPPA) analyses of 103 primary human gynecologic tumors, enriched for patient diversity and germline rs3820282 variant genotype, to determine the impact of the rs3820282/WNT4 axis on tumor biology." (PMID 38112643, 2024). "Findings of these experiments suggest that SIRT6 by targeting the inhibitor WNT4 might modulate insulin secretion from pancreatic β‐cells and thereby probably curtail muscle atrophy associated with tumour growth in Tu‐Sk.T6Tg mice." (PMID 34212132, 2021). "The expression pattern of these receptors suggests that tumour cells are a prime target of WNT4, which could play a role in metastasis‐associated signal transduction pathways and biological processes." (PMID 34841720, 2021). "These analyses identified several differentially methylated genes linked to invasiveness (e.g., PHYHD1, WNT4, STAT6, CDH1, CDH13), aggressive behaviour (e.g., AIP, PDCD1, LINE-1), and tumour regrowth (e.g., TERT, FAM90A1, ING2)." (PMID 41866138, 2026). "IRAK4 knockdown significantly prolonged survival, reduced tumor cell adhesion, downregulated E-cadherin and Wnt4, and induced S-phase/mitotic arrest." (PMID 42146415, 2026). "Gene expression of AIFM3 (p < 0.0001), VGLL4 (p < 0.0001), and WNT4 (p < 0.01) was significantly altered in tumor tissues in comparison to the control tissues." (PMID 39857952, 2025). "And, the WYC-209-inhibited WNT4 and β-catenin protein levels expressed in the xenograft tumor tissues were reversed by WNT4 overexpression, besides, the facilitated cell apoptosis induced by WYC-209 was also abrogated." (PMID 38178596, 2024). "In summary, our data revealed that WYC-209 showed an anti-tumor effect on GC both in vitro and in vivo by down-regulating the expression of WNT4 via RARα, making it a prospective strategy in antitumor therapy." (PMID 38178596, 2024). "By integrating transcriptome sequencing data, 19 m6A-modified genes were found to be upregulated in tumor tissues, leading to the development of a three-gene (EME1, WNT4, SHISA2) risk prognosis model." (PMID 39726587, 2024). "Our observations integrate proteomic, metabolomic, and transcriptomic studies in cell lines, primary human tumor samples, and various public datasets and suggest that convergent mechanisms of WNT4 dysregulation drive cancer metabolism." (PMID 38112643, 2024). "In order to further prove that NE can regulate the expression level of WNT7A, we detected the expression levels of Wnt1, Wnt2, Wnt3a, Wnt4, Wnt5a, Wnt6, Wnt7a and Wnt10a in tumour tissues of anti-PD-1 mAb + Vehicle and NE + anti-PD-1 mAb + Vehicle groups." (PMID 36646807, 2023). "The results of our study suggest that the WNT4 protein cannot be directly attributed to tumor invasion and development, but the WNT4 gene has the potential to be a marker of functional estrogen signaling in EEC." (PMID 37835474, 2023). "An alteration in WNT4 expression was found in different histological tumor types in a large group of EC patients." (PMID 37835474, 2023). "In hypoxia, Wnt4-loaded exosomes secreted by the tumour cells promoted angiogenesis through the proliferation and migration of ECs via activated Wnt/β-catenin signalling." (PMID 36766788, 2023). "In the group of patients with tumor located within the uterus (T1-T2 group) or tumor extended beyond the uterus (T3-T4 group); WNT4 mRNA gene expression was lower when compared to control (p < 0.001, p < 0.05, respectively)." (PMID 37835474, 2023).
tumor (continued). "Apparently, this abnormality is an intrinsic property of the tumor cells, since 3D cultures of neoplastic TECs showed stronger WNT4 expression and secretion for longer periods than parallel 2D neoplastic TEC cultures from the same tumors." (PMID 35965500, 2022). "Hypoxia stimulates tumor cells to release Wnt4-rich exosomes that are delivered to normoxic cells to enhance prometastatic behaviors, including enhanced tumor invasion and migration." (PMID 36233088, 2022). "Nevertheless, we have shown that high Wnt-4 expression in healthy tissue decreases in low-grade tumors, but then increases in high-grade tumors, suggesting that tumor progression requires Wnt-4 activation or reactivation." (PMID 34945091, 2021). "In our study we have shown that high Wnt-4 expression in healthy tissue decreases in low-grade tumors but then increases in high-grade tumors, suggesting that tumor progression requires Wnt-4 activation or reactivation." (PMID 34945091, 2021). "As proof of principle, we demonstrate a tumour‐promoting function of the highly cell‐selective mediator WNT4 produced by CAF and acting on tumour cells to induce their migration." (PMID 34841720, 2021). "The central role of stroma‐derived mediators is exemplified by (i) WNT4 stimulating tumour cell adhesion and migration, (ii) activation of pro‐inflammatory signaling by extracellular HSP70 and (iii) CSF1 inducing macrophage proliferation." (PMID 34841720, 2021). "Len-sh-circ_PVT1 promotedhe texpression of DKK1, NKD1, and p-GSK3β and inhibited wnt4 and β-catenin in tumor." (PMID 34336825, 2021). "Using conditioned media (CM) from these cells, we investigated the impact of WNT4 on tumour cell motility and migration as well as tumour cell adhesion to the mesothelial layer." (PMID 34841720, 2021). "Several Wnt genes were induced by MAPKi treatment in BPN tumor cells, including Wnt2b, Wnt4, Wnt8b, and Wnt10b." (PMID 33821796, 2021). "Immunohistochemical analysis of WNT4 in tumor tissue arrays indicated that the level of WNT4 was elevated in 45/63 (71.43%) of tumors." (PMID 33222684, 2020). "We identified that high WNT4 expression is associated with similar mTOR pathway activation in ILC and serous ovarian cancer tumors, suggesting that WNT4 signaling is active in multiple tumor types." (PMID 33053661, 2020). "To examine WNT4-driven signaling in tumor tissues, we explored data from The Cancer Genome Atlas (TCGA) using the cBio Portal." (PMID 33053661, 2020). "Together, these data highlight WNT4 as a novel and highly potent factor that drives conversion of NFs into CAFs within the tumor microenvironment." (PMID 33222684, 2020). "Subsequently, CM from fresh tumor and adjacent normal tissues was collected to identify the source of WNT4 hypersecretion." (PMID 33222684, 2020). "In tumor xenografts, silencing E6 resulted in reduced protein amounts of WNT4 and JIP2, as shown by immunohistochemistry (IHC), which was consistent with what we observed in HeLa cells cultured in vitro." (PMID 31637011, 2019). "Expression levels the remaining Wnt ligands, including Wnt1, Wnt3, Wnt4, Wnt5A, Wnt8A, Wnt9B, Wnt10A and Wnt16, remained insignificantly different between liver tumors tissues and adjacent non-tumor tissues." (PMID 30814912, 2019). "Wnt-4 overexpression is observed in most PAs, and Wnt-4 excessive activation is inversely correlated to tumor invasion." (PMID 32922863, 2018). "Activators of the Wnt pathway, such as WNT4, can be classified as tumor promoters." (PMID 39857952, 2025). "WYC-209 exerts anti-tumor effects in GC by down-regulating the expression of WNT4 via RARα." (PMID 38178596, 2024). "Furthermore, WNT4 mRNA expression was significantly reduced in EC samples categorized depending on primary tumor status compared to the control (C vs. T1, p < 0.001; C vs. T2, p < 0.05; C vs. T3, p < 0.05)." (PMID 37835474, 2023). "The WNT4 gene expression was also decreased in EC samples categorized by the tumor characteristics." (PMID 37835474, 2023).
tumor (continued). "Thus, while the tumor-promoting effects of estrogens can be maintained, the activation of WNT4 gene expression can be neglected." (PMID 37835474, 2023). "Learning about the influence of the WNT4 protein on intracellular processes, such as metabolism regulation, tumor cell proliferation, and the formation of tumor blood vessels, will enable subsequent studies of tumor reemission, metastasis, and chemoresistance." (PMID 37835474, 2023). "Considering our new observations, WNT4 is also expressed by thymocytes and may foster tumor cells in a paracrine way." (PMID 35965500, 2022). "It has already been shown that Wnt-4 secreted by tumor tissue promotes cancer progression." (PMID 34945091, 2021). "There was higher expression of Wnt-4 in healthy than in tumor tissue." (PMID 34945091, 2021). "Several single nucleotide polymorphism (SNPs) have been associated with the disease, for example in the region of the wingless-type mammalian mouse tumor integration site family member 4 (WNT4), vezatin (VEZT) and follicle stimulating hormone beta polypeptide (FSHB)." (PMID 34544404, 2021). "However, with tumour background, upregulated WNT4 plasma levels were significantly downregulated in Tu‐Sk.T6Tg, compared with in Tu‐CN mice." (PMID 34212132, 2021). "Interestingly, WNT4 levels were decreased after radical surgery in 21/23 (91.30%) of CRC patients who underwent surgery treatment to remove the tumor (P < 0.05)." (PMID 33222684, 2020). "Angiogenesis is critical in tumor development, therefore, we next studied whether WNT4 could promote angiogenesis in CRC." (PMID 33222684, 2020). "Tumor volume and weight were decreased in the PRMT5-depleted group, whereas Wnt4 overexpression could reverse PRMT5-silencing tumor shrinkage." (PMID 33060569, 2020). "Wnt4, a member of the Wnt family, has been shown to participate in tumor carcinogenesis." (PMID 33060569, 2020). "Tumor growth inhibition induced by knockdown of PRMT5 was restored by ectopic expression of Wnt4." (PMID 33060569, 2020). "The similar signaling pathways associated with WNT4 in ILC and OvCa may parallel the critical role of WNT4 in both tissues of origin, and related tumor biology." (PMID 33053661, 2020). "Taken together, these results may indicate that WNT4 only has a slight effect on tumor proliferation." (PMID 33222684, 2020). "Combined with our results, we speculated that WNT4 secreted by CRC tissue mainly acted on the tumor microenvironment to create an environment that is conducive to tumor growth, while WNT4 in serum may simply act as a diagnostic or prognostic indicator for CRC." (PMID 33222684, 2020). "The DNA methylation and expression levels of PHYHD1, LTBR, MYBPHL, C22orf42, PRR5, ANKDD1A, RAB13, CAMKV, KIFC3, WNT4 and STAT6 are associated with tumor invasion, and these genes may become the potential genes for targeted therapy." (PMID 31796052, 2019). "The best rescue of tumor growth was observed when both WNT4 and JIP2 were ectopically expressed." (PMID 31637011, 2019). "The proteins of Wnt4, Wnt 5a, Wnt7a, and Wnt14 have been studied in the OS cell lines, implying that Wnt pathway may serve as a tumor activator." (PMID 28665975, 2017). "This may be due to p21 inhibiting cellular growth by pathways not regulating cell cycle, for instance, during notch 1 activation, p21 suppressed E2F1-dependent Wnt4 expression to inhibit tumor cell proliferation." (PMID 28522974, 2017). "Future studies will examine the mechanisms leading to ER control of WNT4 expression, elucidate the components of the WNT4 signaling pathway, and evaluate the role of this pathway in tumor models systems including patient-derived xenografts and primary tumor tissue explants." (PMID 27650553, 2016). "The expression of Wnt4 and β-catenin in tumor tissues was determined by using immunohistochemistry." (PMID 26918831, 2016).
tumor (continued). "It has been also reported that WNT4 interferes with Ras-induced actin cytoskeleton reorganization; it is known that aberrant motility and invasive ability are relevant hallmarks of malignant tumor cells." (PMID 24274766, 2013). "We suggest that the maintenance of appropriate WNT4 expression may also be critical for prevention against tumor initiation." (PMID 24274766, 2013). "Notably, serum Wnt4 concentrations decreased following surgical removal of the tumor." (PMID 40943055, 2025). "Furthermore, elevated levels of Wnt-4 in serum are downregulated after tumor resection." (PMID 34945091, 2021). "As the attachment of tumour cells to a mesothelial cell layer is thought to represent an important step for transmesothelial migration and subsequent metastasis formation, we investigated whether WNT4 max play a role in this context." (PMID 34841720, 2021). "Interestingly, elevated levels of WNT4 in serum were downregulated after tumor resection." (PMID 33222684, 2020). "Compact tumor organoids exhibited a higher expression of genes involved in WNT-mediated maintenance of nephron progenitors (e.g. LGR5, MYCN, HMGA2, LIN28B, NCAM, WNT4, BMP7)." (PMID 39740515, 2025). "Combined expression of WNT ligands (WNT3A, WNT4, WNT7B, WNT9A, WNT10A, WNT11) in BRCA patient tumours has a positive correlation (R = 0.27, p value = 0) with the combined expression of key EMT-inducing transcription factors SNAI1, SNAI2, ZEB1, ZEB2 and TWIST1." (PMID 38678032, 2024). "A recent study found that Wnt4 is highly express in the serum of CRC patients and in tumour tissues." (PMID 36766788, 2023). "The WNT4 transcript level reduction was also observed in the tissue samples of the EEC group (vs. control, p < 0.05), in which the tumor development is estrogen-dependent (p > 0.05)." (PMID 37835474, 2023). "Concomitant overexpression of both FOXC2 and WNT4 has been observed in some cancers, including CRC, suggesting FOXC2-mediated induction of WNT4 in tumor cells as well." (PMID 34298659, 2021). "In this study, we first showed that WNT4 levels were increased in the serum of CRC patients and originated from CRC tissues, and were decreased after tumor resection." (PMID 33222684, 2020). "Results show that leptin signaling increases the expression of tumor progression and chemoresistance-related genes (ABCB1, WNT4, ADHFE1, TBC1D3, LL22NC03, RDH5, ITGB3) in TNBC cells." (PMID 32471192, 2020). "In the present study, we demonstrated for the first time that WNT4 was elevated in the serum of CRC patient and originated from tumor tissues by measuring the CM from colorectal tissue culture, and was decreased after tumor resection." (PMID 33222684, 2020). "WNT4 is one of the family members of WNT, and the expression of WNT4 in PCa has been elucidated as an important factor in both embryonic development and tumor suppression." (PMID 33101546, 2020). "The migration and invasion of CRC cells were determined by trans-well assay, and the effects of WNT4 on CRC invasion and metastasis in vivo were verified by tumor xenograft in nude mice." (PMID 33222684, 2020). "Others have demonstrated that the tumor suppressors p63, p73 and WT1 positively regulate Wnt4 expression while p21 has the opposite effect, suggesting that maintenance of appropriate Wnt4 expression may also be critical for adult tissue homeostasis and prevention against tumor initiation." (PMID 20161747, 2010). "The WNT4 stably overexpressed HGC-27 cell line was generated using lentivirus and after WB and qRT-PCR validation for transfection efficiency (*P < .05), the xenograft tumor models were constructed." (PMID 38178596, 2024). "Wnt4 may also be secreted as exosomes from CRC cells, playing a crucial role in promoting tumour progression in the TME." (PMID 36766788, 2023).
tumor (continued). "While there was no significant change in WNT4 protein expression in gastrocnemius muscle of N.Tu‐CN and N.Tu‐Sk.T6Tg mice, in tumour‐bearing mice, SIRT6 over‐expression significantly reduced its expression in the muscle." (PMID 34212132, 2021). "Although not statistically significant, it shows that Wnt-4 expression is maintained, moreover, it continuously increases with increasing tumor grade." (PMID 34945091, 2021). "Both the WNT4/β-catenin and non-canonical pathway participate in tumor development based on the cell types." (PMID 34642299, 2021). "In our study, we demonstrated that angiogenesis could be activated by WNT4 through the WNT4/β-catenin/ANG2 pathway, which is vital for tumor invasion and metastasis." (PMID 33222684, 2020). "Tumor growth inhibition induced by silencing E6 could be largely restored by ectopic expression of either WNT4 or JIP2, which was shown by measuring the tumor growth curve and Ki-67-positive cells." (PMID 31637011, 2019). "In addition to Wnt3A and Wnt1, upregulation of Wnt3A, Wnt4, Wnt5A, and Wnt10B has also been observed in both tumor tissue and the adjacent non-tumorous liver." (PMID 40943055, 2025). "Furthermore, E6 can selectively upregulate WNT4, JIP1, and JIP2 translation, resulting in the activation of the non-canonical WNT-PCP-JNK pathway through the phosphorylation of mitogen-activated protein kinase to promote cell proliferation and tumor growth." (PMID 39228892, 2024). "Finally, since WNT signaling interacts dynamically with the tumor micro-environment, we extended our study of WNT4 to 3D TET spheroids that were enriched with or without an extracellular matrix." (PMID 35965500, 2022). "Their findings also support our results, wherein we observed that in the tumour setting, SIRT6 over‐expression inhibited WNT4 expression in the skeletal muscle and downregulated circulating levels of WNT4, which might have contributed to maintain plasma insulin levels in Tu‐Sk.T6Tg mice." (PMID 34212132, 2021). "When we compared the tumor size in centimeters for all patients, there was a poor negative correlation between tumor size and Wnt-4 expression, i.e., larger tumors had less Wnt-4 expression (r = −0.1240, p = 0.093, statistical significance at a significance level of 90% (α = 0.1))." (PMID 34945091, 2021). "Similarly, plasma levels of WNT4 did not change significantly with SIRT6 over‐expression in the non‐tumour environment and were barely detectable." (PMID 34212132, 2021). "A poor negative correlation between tumor size and Wnt-4 expression was found." (PMID 34945091, 2021). "Therefore, we speculated that WNT4 could be secreted as exosomes from CRC cells and act on various components in the tumor microenvironment to promote tumor progression." (PMID 33222684, 2020). "In addition, it was also found that p21CIP1, involved in regulation of cellular senescence, functions as a negative transcriptional regulator of WNT4 downstream of Notch 1 and that p21CIP1 potentially reorganizes the nucleus during tumour reversion." (PMID 25821840, 2015). "Although the molecular mechanisms underlying this loop require further definition, this study has shed new light on the targets of non-canonical wnt4 (wat4a) signaling as well as has opened a new window for understanding the mechanism of the EAF gene family in tumor suppression." (PMID 20161747, 2010). "In addition, non-canonical WNT4 signals may be critical in preventing tumor initiation by controlling EAF1 and EAF2/U19 expression in zebrafish and mammals." (PMID 24274766, 2013).